S100A4 (S100 calcium binding protein A4)
Diseases named in the same sentence as S100A4 in open-access papers (continued):
Sharing a sentence is not in itself a finding about the gene and the disease.
tumor (continued). "The fibroblast-specific protein S100A4 promotes tumour growth by stimulating angiogenesis." (PMID 36982551, 2023). "Furthermore, Alcian blue staining was performed to compare the peri-tumor region, which was more intensely stained in the control mice than that in the S100a4-Cre; Ext1f/f mice." (PMID 36809261, 2023). "S100A4 mediates the functions of STC1 on tumor cells and the metastatic microenvironment." (PMID 37400459, 2023). "Additionally, we performed a microarray analysis of MC38 S.C. tumor tissues in S100a4-Cre; Ext1f/f and control mice." (PMID 36809261, 2023). "Prior research unfolded that activated S100A4 signaling due to PCDH7-regulated tumor-astrocyte interaction could retain the self-renewal of TN-BCSCs and modulate their adaptation and colonization." (PMID 37838657, 2023). "However, real-time RT-PCR analysis showed significantly higher expression of Tgfβ1 in the tumor of S100a4-Cre; Ext1f/f mice." (PMID 36809261, 2023). "In addition, lung metastasis lesions showed a clear increase in pErk1/2 and Ki-67 in tumor cells but were inhibited by monoclonal antibody S100a4 or sRAGE." (PMID 36973439, 2023). "The study demonstrated that macrophages, fibroblasts, and tumor cells all could release S100A4 into the tumor microenvironment, and its elevated concentration promoted the formation of a pre-metastatic niche." (PMID 36817446, 2023). "The well-known function of S100A4 is the induction and promotion of tumor metastasis." (PMID 37217870, 2023). "However, statistically significant correlations were observed between S100A4 and other S100s in the tumor array." (PMID 37627239, 2023). "Chromatin-bound S100a4 mediates NEPs effect on metastatic outgrowth and has not been found to be attached to NETs; and tumor cell NEPs do not have NET-associated enzymes such as NE or MPO, which are essential for NET functions." (PMID 36973439, 2023). "In addition, targeting NEPs using DNase, monoclonal antibody S100a4 or sRAGE decreased tumor outgrowth." (PMID 36973439, 2023). "Hence, to investigate how fibroblast HS affects the tumor stromal environment in vivo, we generated fibroblast-specific Ext1 conditional knockout mice by crossing Ext1flox/flox with S100a4-Cre/+ mice." (PMID 36809261, 2023). "Here, we tested the hypothesis that the S100A4/NMMIA axis might contribute to GBM progression through modulation of tumor vascularization." (PMID 35392912, 2022). "The strong correlation between S100A4 expression, metastases development and patient survival might open opportunities to use S100A4 to improve the prognosis of these patients and as a therapeutic target for intervention in this tumor entity." (PMID 35326507, 2022). "For example, several components of the basement membrane (e.g., Collagens, Nidogen-1, Laminin subunit 3) were downregulated in tumor tissue, and proteins involved in Calcium-ion binding (e.g., Annexin-A3, S100A4) showed lower expression levels in tumor tissue than in tumor-adjacent tissue." (PMID 35681609, 2022). "Recent research indicated that S100A4 promotes tumor metastasis and EMT." (PMID 35165531, 2022). "S100A4+ fibroblasts werecharacterized by increased mobility and invasiveness comparedto S100A4– fibroblasts, as well as the ability to secreteS100A4 into the tumor microenvironment (Grum-Schwensenet al., 2005)." (PMID 35342854, 2022). "The major known function of the S100A4 protein is to promote tumor metastasis." (PMID 35154161, 2022). "Also, the poor prognosis of cancer has been correlated with the upregulation of S100A4 in tumor cells, and its expression has been regulated by other factors like β-catenin, epidermal growth factor, tumor necrosis factor alpha (TNF-α), and methylation." (PMID 35965620, 2022). "In human HCC, S100A4 expression is further correlated with tumor aggressiveness and malignancy." (PMID 36232334, 2022). "Depending on the tumor environment, cells could be differentially primed and thus react differently when inhibiting S100A4." (PMID 35326507, 2022).
tumor (continued). "Furthermore, we confirmed that extracellular S100A4 levels increased in LLC-GFP-luc tumour tissues after DOX treatment." (PMID 36207295, 2022). "However, in patients with low-risk staged tumor diseases (UICC I/II, N0, L0, V0 state), S100A4 expression defines their prognosis." (PMID 35326507, 2022). "S100A4+ CAFs promote tumour metastasis through secretion of VEGF-A and Tenascin-C (TN-C)." (PMID 36555218, 2022). "The extracellular function of S100A4 also supports tumor progression." (PMID 33549040, 2021). "Moreover, the Wnt signaling pathway induces expression of S100A4, an important player in tumor progression and metastasis, which in turn positively activates the NF-κB signaling pathway." (PMID 33426510, 2021). "Initial functions attributed to S100A4 were to support metastatization, given its ability to bind and regulate cytoskeletal components, thereby promoting the motility and invasion of several types of tumor cells." (PMID 33918416, 2021). "By binding to calcium, S100A4 affects tumor cell motility and metastasis." (PMID 34148033, 2021). "S100A4 mediates migration of tumor cells via SDC4and α5β1 integrin-mediated PKCα activation." (PMID 34282767, 2021). "Therefore, the role of S100A4-dependent PPAR-γ induction as a mechanism to reduce tumor immunogenicity and evade immune surveillance deserves further exploration." (PMID 34145030, 2021). "High levels of S100A4 promoted tumor cell migration and decreased the efficacy of cisplatin." (PMID 33391538, 2021). "In the primary tumor, S100A4 was expressed in the areas of stroma and fibrosis." (PMID 34078355, 2021). "Collectively, the results indicated that CXCL12/CXCR4 might promote PNI by provoking the tumour cell to differentiate towards Schwann‐like cell through Twist/S100A4 axis in SACC." (PMID 34170080, 2021). "S100A4 is a well-known tumor promoting gene and is the most studied one in HCC." (PMID 33815482, 2021). "Tumors with high S100A4 expression present higher tumor initiation and spheroid ability." (PMID 34148033, 2021). "S100A4 released by tumor and stromal cells within the tumor microenvironment may contribute to cell proliferation, invasion, angiogenesis, and metastasis." (PMID 33946884, 2021). "S100A4+ MAFs in metastases attenuate apoptotic stress for tumor cells to support metastatic colonization by producing tenascin-C, an ECM protein that provides survival protection and likely functions via cooperative interaction with receptors or the promotion of the CSC phenotype." (PMID 34112258, 2021). "S100A4 is an important effector in tumor migration and invasion processes." (PMID 33789743, 2021). "Next, we explored the roles of S100A4+ TAMs in tumor development using two S100A4-KO mouse models." (PMID 34145030, 2021). "S100A4 is overexpressed in a range of different tumor types." (PMID 34768862, 2021). "We observed that systemic S100A4 deficiency markedly impeded tumor growth and caused a significant decrease in tumor weight but did not affect the body weight of the mice." (PMID 34145030, 2021). "The cells expressing Vimentin, S100A4, and αSMA are likely to be resting or activated fibroblasts that may play an important role in this type of neoplasia." (PMID 33761962, 2021). "The expression of S100A4 is related to the development and final outcome of the tumor." (PMID 33912559, 2021). "In this aspect, it was demonstrated that the expression of S100A4 in co-cultured astrocytes surrounding C6 cells could positively correlate with tumor motility." (PMID 33918416, 2021). "In many cancers, S100A4 has been shown to stimulate tumor proliferation and metastasis." (PMID 33256110, 2020). "Many cells including tumors of different origins, fibroblast subtypes in the heart, microglia in the central nervous system and macrophage subpopulations derived from bone marrow express S100A4 for multiple purposes such as tumor metastasis, tissue repair, and inflammation." (PMID 33315931, 2020).
tumor (continued). "Moreover, S100A4 recruits the factors of the immune system, or remodeling the extracellular matrix in the tumor–stroma microenvironment aggravates metastasis formation." (PMID 33117687, 2020). "LncRNA PTCSC3 was significantly suppressed in PTC tumor tissue and it could affect PTC predisposition and carcinogenesis through downregulating the MMP-9 and VEGF expression via the S100A4 pathway." (PMID 32284745, 2020). "The most well‐known function of S100A4 is to induce and promote tumour metastasis." (PMID 32307910, 2020). "S100A4+ CAFs promote tumor metastasis through secretion of VEGF- A and Tenascin-C." (PMID 33292666, 2020). "Moreover, in the context of a pre-metastatic niche, S100A4 production serves as a link between inflammation and tumor metastasis, and is indicative of poor prognosis." (PMID 32290283, 2020). "In addition, the expression levels of S100A4 were found to be considerably related to tumor size, tumor differentiation, TNM stage, and lymphatic invasion in PC patients." (PMID 31526392, 2019). "S100A4(+) CAFs decreased during tumor progression, as less S100A4(+) CAFs could be detected in vehicle treated mice." (PMID 30741922, 2019). "To address whether our observation is relevant to the activation of S100A6 and S100A4 in tumours, we assessed the expression of pSTAT3 in PDAC specimens by IHC." (PMID 31123345, 2019). "CYR61 or S100A4 are suggested to be valuable prognostic markers regarding several tumor entities." (PMID 31709177, 2019). "Given that the number of double mutant tumors with S100A4 expression data in this set is much lower than the single mutant tumors, analysis of a larger cohort of double mutant tumors with the tumor stage-specific information will help further confirm the role of S100A4 in metastasis." (PMID 31881983, 2019). "Recently, other molecules, including S100A4, have been reported as tumor markers for diagnosing PC." (PMID 31526392, 2019). "S100A4 has been shown to attract T cells to the primary tumor and the pre-metastatic niche." (PMID 30483898, 2019). "However, the detailed mechanisms by which S100A4 interacts with autophagy in tumor development still need further investigation." (PMID 29449540, 2018). "As compared to CD133− patients, tumor cells in CD133+ patients demonstrated high levels of TGF-β/p-Smad2 as well as EMT-like alteration, characterized by loss of E-Cadherin and expression of Vimentin and S100A4." (PMID 29510695, 2018). "Moreover, S100A4 inhibited starvation-induced autophagy and promoted tumor cell proliferation by activating the Wnt/β-catenin pathway in a receptor for advanced glycation end products (RAGE)-dependent manner." (PMID 29449540, 2018). "As the nodal stage of the tumor advanced, the rate of the S100A4 protein expression increased." (PMID 30111999, 2018). "To determine the intracellular pathways involved in the inhibition of MDSC apoptosis by exogenous S100A4, we incubated primary splenic MDSCs from tumor-bearing mice with recombinant S100A4 and studied the early kinetics of activation of downstream pro-survival factors." (PMID 29556233, 2018). "Several works have also demonstrated that S100A4 may have oncogenic effects in a multitude of tumor types." (PMID 30045697, 2018). "High expression of S100A4 has been observed in NSCLC and was associated with differentiation and metastasis of tumor cells; however, our results showed that S100A4 was not significantly related to OS in NSCLC." (PMID 29607329, 2018). "Additionally, S100A4 inhibited starvation-induced autophagy to promote tumor cell viability via the Wnt pathway." (PMID 29449540, 2018). "S100A4 is expressed in a variety of cells, such as fibroblasts, macrophages, lymphocytes and malignant cells, and plays a crucial role in mediating the interplay between the tumor and stroma." (PMID 29449540, 2018).
tumor (continued). "Similar to results with MC205 cells, reduced tumor growth was observed in S100A4−/− mice compared with that in WT mice with B16F10- or LLC-derived tumors; this became significant 17 days after tumor-cell inoculation and the differences increased until the end of the experiments." (PMID 29556233, 2018). "Furthermore, the high expression of S100A4 was significantly correlated with advanced tumor grades and tumor size, while there was no significant relation between high S100A4 expression and age factors as well as sex features." (PMID 29449540, 2018). "As the stage of the tumor advanced, the rate of the S100A4 protein expression increased." (PMID 30111999, 2018). "Furthermore, a calcium-binding protein, S100A4, which is frequently upregulated in tumor cells, was downregulated by PD407824." (PMID 29507695, 2018). "Other examples of paracrine signalling that is deregulated by CAFs include the secretion of chemokine CXCL12 with subsequent tumour growth facilitation and the expression of intra-cellular and extracellular Ca2+-binding protein S100A4 with subsequent tumour progression and metastatic spread." (PMID 29362402, 2018). "The antihelmintic medication niclosamide displays its anticancer effects by inhibiting the S100A4 promoter activity and by inhibiting the Wnt/β-catenin signaling pathway, which is a major regulatory pathway for the initiation of cancer, tumor growth, cell differentiation, and metastasis." (PMID 30111999, 2018). "The 6B12, an S100A4 neutralizing antibody, was able to restore the Th1/Th2 polarization balance and inhibit T cell migration to the early primary tumor lesions and pre-metastatic lungs, in turn, suppressing tumor cell growth and metastasis." (PMID 29069865, 2017). "Moreover, in a cohort of 59 CRC patient tumor specimens miR-520c-3p was significantly downregulated (p = 0.003) compared to the normal mucosa tissues and its target S100A4 was significantly upregulated (p = 0.018)." (PMID 28423501, 2017). "Furthermore, extracellular S100A4 released by tumor and/or stromal cells alters the tumor microenvironment and enhances pro-metastatic activities such as stimulation of angiogenesis and numerous effects on leukocytes." (PMID 29069865, 2017). "Here, we summarize the role of S100A4 in non-tumor pathophysiologies, including fibrosis, inflammation, immune responses, neuroprotection, and angiogenesis, and some common non-tumor diseases as well as the possible molecular pathways in which S100A4 is involved and its potential clinical value." (PMID 29204268, 2017). "PCA-based characterization of two cell lines revealed that the increased motility and invasion in TMD cells, tumor-derived cells, than BMD cells, harvested from bone metastasis, was linked to the elevated expression level of S100A4 calcium-binding protein and functionality of GRM3." (PMID 28615627, 2017). "Notably, with Ttl, S100a4, Zfx, Cct3, Stat3, Stab1 and Bmx, 7/20 found candidate genes have been reported as proliferation-related in tumor cells too." (PMID 29228606, 2017). "In addition to malignant tumors, S100A4 plays an important role in many kinds of pathological process and non-tumor diseases including fibrosis, inflammation, immune response, neuroprotection, and angiogenesis." (PMID 29204268, 2017). "In addition to being expressed in tumor cells, S100A4 is expressed in many normal cells, including fibroblasts, macrophages, lymphocytes, neutrophils, vascular cells, and bone marrow-derived cells." (PMID 29204268, 2017). "The intracellular S100A4 is found to increase the stability of lamellipodia and enhance chemotactic cell migration via the interaction with NMIIA, and is therefore associated with an increase in the formation of metastases and tumor cell spread." (PMID 29069865, 2017). "It is reported that S100A4 neutralizing antibody suppresses spontaneous tumor progression." (PMID 28615627, 2017).
tumor (continued). "Sulindac-downregulated β-catenin expression led to the reduction of S100A4 nuclear accumulation and subsequent TCF- binding, which in turn resulted in the inhibition of tumor cell migration and invasion; it could be rescued by ectopic S100A4 overexpression." (PMID 29069865, 2017). "In addition to the role of S100A4 in cancer progression and metastasis, this protein was recently found to be involved in some vital non-tumor pathophysiologies in humans, which has attracted much attention." (PMID 29204268, 2017). "Moreover, other representatives of the S100 family such as S100A4 and S100P were shown to be overexpressed in CCA tumor samples and were associated with increased tumor invasiveness." (PMID 27709523, 2016). "S100A4 secreted by tumor and stromal cells, is a member of the S100 calcium-binding protein family." (PMID 27576342, 2016). "Such a distinct feature of S100A4 in promoting tumor metastasis, thereby also known as metastasin, makes it a strong candidate as a biomarker for predicting disease progression, particularly tumor metastasis, and clinical prognosis." (PMID 26903691, 2016). "Therefore, there is a need for therapeutic options to either reduce the expression level of S100A4 in the tumor or its environment, or to interfere with downstream effects of the protein, like protein-protein interactions and signaling pathway modulation." (PMID 27331819, 2016). "On the other hand, tumor cells but not TAMs express ERB2, encoding a receptor for S100A4, suggesting a tumor-selective effect." (PMID 27215396, 2016). "Indeed, accumulated S100A4 has been found at sites of plasma membrane repair, pointing to a role of S100A4 in maintaining the invasive potential of tumor cells." (PMID 27331819, 2016). "S100A4 has a role in tumour progression and metastasis and is involved in NSCLC54 metastases." (PMID 26759080, 2016). "S100A4 was present in the networks of two tumor lines (GBM10 and GBM59))." (PMID 27354287, 2016). "Design of novel therapies aiming at the mesenchymal, stem‐cell‐like state might thus be beneficial also for the S100A4‐positive subpopulation of tumor cells." (PMID 27273130, 2016). "Immunohistochemical staining of S100A4 in tumor tissue and gene specific quantification of micro-dissected S100A4-mRNA by quantitative reverse-transcription (q-RT) PCR showed higher S100A4 expression in patients, who developed metachronous metastases within 36 months." (PMID 27331819, 2016). "There, S100A4 and also β-catenin were found higher expressed in the tumor invasive margin." (PMID 27331819, 2016). "Moreover, S100A4 expression has correlated with tumor metastasis and poor prognosis of patients with several types of cancer, including PC." (PMID 26903691, 2016). "By implementing two different mouse models we demonstrate that the S100A4 function blocking antibody suppresses spontaneous tumor progression and pre-metastatic niche formation which correlates with suppression of T-cell accumulation both at the site of primary tumor and in pre-metastatic lungs." (PMID 25884510, 2015). "Furthermore, it has been shown that S100A4 acts as an angiogenic factor, as well as attracting T-cells to the site of the growing tumor and pre-metastatic lungs." (PMID 25884510, 2015). "Given that endothelial S100A4 can be a molecular target for inhibiting tumor angiogenesis, we addressed here whether synthetic peptide capable of blocking S100A4-effector protein interaction could be a novel antiangiogenic agent." (PMID 26029719, 2015). "Some evidence suggests that S100A4 may regulate tumor progression through modulating the tumor environment." (PMID 25677816, 2015). "One could speculate that mechanisms involved S100A4-dependent attraction of T-cells to the tumor and spleen are similar." (PMID 25884510, 2015).